CTLA4 (cytotoxic T-lymphocyte associated protein 4)
Diseases named in the same sentence as CTLA4 in open-access papers (continued):
Sharing a sentence is not in itself a finding about the gene and the disease.
malignant pleural mesothelioma (14 papers, 2017 to 2025). A malignant neoplasm that arises from mesothelial cells in the pleura and shows a diffuse growth pattern. "The patient, a 73‐year‐old male, had undergone combination therapy for malignant pleural mesothelioma for 2 years, utilizing both ipilimumab (a CTLA‐4 inhibitor) and nivolumab (a PD‐1 inhibitor)." (PMID 39467776, 2024). "The authors reported on the long-term outcomes of combining ipilimumab (anti-CTLA-4) with nivolumab (anti-PD-1) in patients with unresectable malignant pleural mesothelioma." (PMID 39768223, 2024). "Human malignant pleural mesothelioma (hMPM) is a highly aggressive cancer for which immunotherapy with nivolumab + ipilimumab (anti PD-1 + anti CTLA-4, respectively) is the standard-of-care." (PMID 36685577, 2022). "CTLA4 overexpression was also found to be a positive prognostic marker in nasopharyngeal cancer and malignant pleural mesothelioma." (PMID 33014010, 2020). "In contrast, malignant pleural mesothelioma showed a favourable effect of CTLA-4 overexpression." (PMID 39286684, 2024). "In addition, we observed a favorable effect of CTLA-4 overexpression on OS in malignant pleural mesothelioma, which may due to the complexity of CTLA-4 functions." (PMID 28211499, 2017).
pancreatic adenocarcinoma (14 papers, 2013 to 2025). "In preclinical models of pancreatic adenocarcinoma, we similarly found that anti-CTLA4 is ineffective as a single agent." (PMID 32866185, 2020). "We ascertained in vitro whether pancreatic adenocarcinoma (PDAC)-associated IMC subsets are induced by tumor-derived soluble factors and whether they are immunosuppressive focusing on the inhibitory co-stimulatory molecules PDL1 and CTLA4." (PMID 23359812, 2013). "Clinical translation has yielded two FDA-approved anti-CTLA-4 monoclonal antibodies for pancreatic adenocarcinoma: ipilimumab (anti-CTLA-4 IgG1κ) and tremelimumab (anti-CTLA-4 IgG2)." (PMID 41209702, 2025). "CircUBAP2 (hsa_circ_0007367) was shown to repress antigen presentation and induce immune escape in pancreatic adenocarcinoma (PAAD) through sponging miR-494 to upregulate CXCR4 and ZEB1 proteins, then leading to increased expression of CTLA-4 and PD-1." (PMID 38177102, 2024). "In a mouse model of pancreatic adenocarcinoma (PAAD), Feig C and colleagues found that the depletion of FAP positive cells contributed to improved anti-CTLA-4 or anti-PD-L1 immunotherapy efficacy, revealing the immune suppressive effect of FAP in cancers." (PMID 37325617, 2023). "“Profile-B” is made by the 6 molecules differently expressed in Pancreatic adenocarcinoma (PAAD) patients (i.e., TIM3 (HAVCR2), OX40 (TNFRSF4), GITR (TNFRRSF18), TIGIT, LAG3 and CTLA4)." (PMID 36224560, 2022). "Interestingly, in the murine pancreatic adenocarcinoma model Panc02.OVA with high susceptibility to ICI, tumor-intrinsic MLKL deficiency did not impact anti-CTLA-4-mediated tumor control and had only minor negative effects on tumor-bearing mice undergoing anti-PD-1 monotherapy." (PMID 40345706, 2025).
parasitemia (14 papers, 2009 to 2024). "Further work is required to determine if upregulation of CTLA‐4 in these settings arises to prevent pathogenic responses potentially caused by persistent low parasitemia infections." (PMID 35475529, 2022). "Recently, several studies have reported that immune checkpoints, including PD-1, CTLA-4, LAG-3, TIM-3, TIGIT, etc., were associated with immune tolerance and immune escape in parasitic infections." (PMID 39456030, 2024). "Previously, researchers determined the contribution of CTLA-4 to the regulation of immune cell responses and mechanisms of immunosuppression during other parasitic infections, such as Plasmodium." (PMID 39456030, 2024). "As proof of concept, we demonstrated a role for CTLA‐4 in the development of asymptomatic recrudescent parasitemia in infection models." (PMID 35475529, 2022). "Whereas frequencies of CTLA‐4+ TREG cells returned to normal levels after resolution of peak parasitemia, they remained significantly higher than uninfected controls among CD4+ T cells when mice were experiencing asymptomatic recrudescence on day 20 p.i." (PMID 35475529, 2022). "When animals were experiencing peak parasitemia on day 8 p.i., the percentage of CTLA‐4+ cells significantly increased in both TREG and CD4+ T‐cell compartments." (PMID 35475529, 2022). "As proof of concept, we demonstrated a role for CTLA‐4 in the development of asymptomatic parasitemia in infection models." (PMID 35475529, 2022). "In contrast, acute T. cruzi-infected mice treated with anti-CTLA-4 show reduced parasitemia and mortality compared to mice treated with an isotype control (IgG)." (PMID 31105709, 2019). "Using multivariate regression analysis with likelihood ratio test, we found CTLA-4 to be a strong predictor of parasitemia levels." (PMID 31316497, 2019). "The proportion of PD-1+ and CTLA-4+CD4+ T cells weakly correlated with parasitemia at time of diagnosis." (PMID 29555909, 2018). "CTLA-4 and PD-1 are usually expressed after T cell receptor-antigen interaction and expression levels here correlated moderately with parasitemia." (PMID 29555909, 2018). "Our results show a significant increase of circulating CD4+CD25+FoxP3+GITR+ and CD4+CD25+FoxP3+CTLA-4+ lymphocytes in P. vivax-infected donors, which was further correlated with level of parasitemia observed in the same individuals." (PMID 20224778, 2010). "CTLA-4 also contributes to immune regulation and pathology in animal models of bacterial or parasitic infection." (PMID 19247441, 2009). "A recent study has found that exhaustion-specific genes including CTLA-4 are upregulated in advanced-stage AE patients and may contribute to chronic parasite infection." (PMID 39456030, 2024). "While CTLA‐4 blockade improved control of acute parasitemia in mice, it was also found to worsen experimental cerebral malaria disease outcomes, suggesting a protective role for this receptor in the development of T cell‐mediated organ‐specific syndromes during acute infection." (PMID 35475529, 2022). "Importantly, in the symptomatic group, the expression of CTLA-4 was a major predictor in determining parasitemia load." (PMID 31316497, 2019). "Besides, peak parasitemia and highest frequencies of CTLA4+ and PD1+CD4+ T cells might occur at later time points than time of diagnosis." (PMID 27802341, 2016). "Although there have been some studies of PD-1 and CTLA-4 in parasitic infections, the roles played by PD-1 and CTLA-4 in the host immune response have not been fully elucidated in E. multilocularis infection." (PMID 39456030, 2024). "However, using the multiple linear regression model and performing a likelihood ratio test, expression levels of CTLA-4 on both CD4+ and CD8+ T cells were found to significantly predict the level of parasitemia in the symptomatic children." (PMID 31316497, 2019). "By contrast, we found that the degree of parasitemia at time of diagnosis did not correlate with the frequency with which CD4+ T cells expressed CTLA4 or PD1." (PMID 27802341, 2016).
parasitemia (continued). "Thus, a correlation between CTLA4 and PD1 expression and complete parasite biomass or peak parasitemia cannot fully be excluded." (PMID 27802341, 2016). "In addition, the Treg-cell activation markers CTLA-4 and CD39 significantly increased after parasitic infection." (PMID 25522145, 2014). "Similar significant correlations were also observed between parasitemia and absolute numbers of Treg expressing GITR (Rs = 0.66, P = 0.0017), CTLA-4 (Rs = 0.47, P = 0.0349), IFN-γ (Rs = 0.52, P = 0.0187), TGF-β (Rs = 0.66, P = 0.0016), IL-10 (Rs = 0.59, P = 0.0067) and IL-17 (Rs = 0.68, P = 0.0011)." (PMID 20224778, 2010). "CTLA-4 and PD-1 but none of the other markers correlated moderately with parasitemia." (PMID 29555909, 2018). "However, it is also conceivable that the lack of correlation between parasitemia and CTLA4 and PD1 expression in our study reflects the fact that the parasite-induced upregulation of coinhibitor expression is readily saturated by antigen-load and cannot be further increased by higher parasitemia." (PMID 27802341, 2016). "PD-1, CTLA-4, and TIM-3 blockade reduced disease severity in a mouse parasite infection model but could not provide sterilizing immunity or reverse susceptibility to second lethal infection." (PMID 36439147, 2022).
Adrenal insufficiency (13 papers, 2019 to 2025). Insufficient production of steroid hormones (primarily cortisol) by the adrenal glands. "Younger age, male sex, and combination therapy of anti-PD-1 and anti-CTLA-4 were associated with adrenal insufficiency." (PMID 40503677, 2025). "A recent cohort study of 691 patients with autoimmune adrenal insufficiency reported that variants of the CTLA4 gene would increase susceptibility to adrenal insufficiency." (PMID 34887872, 2021). "The results showed that anti‐CTLA‐4 was associated with higher rates of both high‐grade and serious‐grade adrenal insufficiency, with rates of 5.32% and 0.42%, respectively." (PMID 31679184, 2019). "Adrenal insufficiency was less common overall (4–14%), but more often observed under anti-CTLA-4 therapy." (PMID 41301042, 2025). "The incidence of adrenal insufficiency was 17.0% in combination therapy, 4.7% in anti-PD-1 therapy, 2.2% in anti-PD-L1 therapy, 4.2% in anti-CTLA-4 therapy, and 1.8% in sequential therapy of anti-PD-1 and PD-L1." (PMID 40503677, 2025). "CTLA4 is one of the components, and heterozygous deficiency of the protein gives rise to inappropriate polyclonal T-cell activation, leading to highly variable features of autoimmune responses, which may include endocrinopathies of adrenal insufficiency, T1DM, and thyroiditis." (PMID 34887872, 2021).
autoimmune lymphoproliferative syndrome (13 papers, 2019 to 2025). Autoimmune lymphoproliferative syndrome (ALPS) is a rare, inherited disorder characterized by non-malignant lymphoproliferation, multilineage cytopenias, and a lifelong increased risk of Hodgkin's and non-Hodgkin's lymphoma. "To date, 30 pathogenic and 11 likely pathogenic variants of the CTLA-4 gene have been reported in association with autoimmune lymphoproliferative syndrome, according to ClinVar." (PMID 41009791, 2025). "Workup for this lymphadenopathy revealed that the patient has a genetic variant (CTLA4 pathogenic mutation) of autoimmune lymphoproliferative syndrome." (PMID 40932816, 2025). "Heterozygosity for loss-of-function mutations in CTLA4 gives rise to an autosomal dominant autoimmune lymphoproliferative syndrome (Type V MIM# 616100) with incomplete penetrance." (PMID 31572362, 2019).
endometriosis (13 papers, 2016 to 2025). The growth of functional endometrial tissue in anatomic sites outside the uterine body. "Higher soluble circulating CTLA-4 levels in patients with endometriosis are associated with chronic inflammation." (PMID 40508002, 2025). "Our findings shed light on the potential of CTLA-4 in developing new diagnostic and therapeutic approaches in endometriosis management." (PMID 33668701, 2021). "Interestingly, previous evidence demonstrates that CTLA-4 may be implicated in the pathogenesis of endometriosis, but the exact mechanisms are still unclear, and the data are conflicting." (PMID 38892453, 2024). "Patients with severe endometriosis had significantly higher levels of CTLA-4+T cells than those with mild endometriosis." (PMID 41188339, 2025). "On that basis, receptor CTLA-4 can be engaged in the pathogenesis of endometriosis, but it will take time to present the precise regulatory mechanism of the presented ICPs in EMS implant development." (PMID 38892453, 2024). "Chinese researchers demonstrated that CTLA-4 blockade directly inhibits the autoimmune response in vitro in a mouse model of endometriosis." (PMID 35805112, 2022). "We included observational or prospective human and animal studies with any features related to endometriosis and/or infertility studies involving CTLA4-related pathogenesis published in English." (PMID 36142815, 2022). "Levels of CTLA-4+ T cells were significantly higher in patients with more advanced endometriosis than in those with less advanced disease." (PMID 33668701, 2021). "The concentration of soluble CTLA-4 antigen in the peripheral blood plasma was significantly higher in women with endometriosis (mean, 7.12; SD, 1.55) than in the control group (mean, 6.13; SD, 1.52; p = 0.01)." (PMID 33668701, 2021). "Our findings highlight the potential implication of CTLA-4 in the pathogenesis of endometriosis-related infertility and expression of CTLA-4 antigen on lymphocytes as a putative biomarker of this condition." (PMID 33668701, 2021). "The concentration of CTLA-4 antigen in the peritoneal fluid in patients with endometriosis ranged from 0.19 to 7.56, and the mean (SD) was 2.56 (1.90) ng/mL." (PMID 33668701, 2021). "CTLA-4 blockade directly inhibits the autoimmune response in vitro in a mouse model of endometriosis." (PMID 33668701, 2021). "In our study, a significantly higher expression of the CTLA-4 antigen was observed among CD8+T cells in the peripheral blood in patients with endometriosis than in the control group." (PMID 33668701, 2021). "The severity of endometriosis was weakly correlated with the percentage of CD19+CTLA-4+ B cells (Spearman’s R = 0.315, p = 0.02)." (PMID 33668701, 2021). "Recently, patients with endometriosis were reported to have higher percentage of Treg cells expressing CTLA-4 in plasma than healthy individuals." (PMID 33668701, 2021). "Patients with endometriosis had significantly higher percentage of CD8+CTLA-4+ T lymphocytes expressing the CTLA-4 antigen in the peripheral blood than individuals from the control group (p < 0.001)." (PMID 33668701, 2021). "Data suggest that significantly higher percentages of CD4+/CTLA4 and CD8+/CTLA4 T lymphocytes have been observed in patients with endometriosis and intraoperative adhesions, implicating that there is a possible correlation between the ratio of CD8+ T/CD4+ T and endometriosis-related infertility." (PMID 36142815, 2022). "Both groups found that CTLA4 gene variants do not play a role in the pathogenesis of endometriosis, with or without related female infertility." (PMID 36142815, 2022). "Experiments in a mouse model on the therapeutic potential of the anti-CTLA-4 antibody have shown that it may be an important tool to inhibit the progression of endometriosis by regulating the overproduction of CD4+ CD25+ Treg cells, a phenomenon repeatedly reported in the literature." (PMID 35805112, 2022).
endometriosis (continued). "Experiments on the therapeutic potential of the anti-CTLA-4 antibody in a mouse model have shown that it may be an important tool in inhibiting the progression of endometriosis by regulating the overproduction of CD4+CD25+ Treg cells, a phenomenon repeatedly described in the literature." (PMID 33668701, 2021). "Moreover, the positive correlation of the CTLA-4 T-cell rate with the severity of endometriosis makes the CTLA-4 molecule valuable in developing new approaches to understanding and eliminating endometriosis, but more research is needed to confirm this potential." (PMID 33668701, 2021). "At the same time, a positive correlation was reported between the stage of endometriosis and the percentage of CD4+CTLA-4+ T lymphocytes and CD8+CTLA-4 T lymphocytes." (PMID 35805112, 2022). "At the same time, a positive correlation was demonstrated between the stage of endometriosis and the percentage of CD4+CTLA-4+ T cells and CD8+CTLA-4 T cells." (PMID 33668701, 2021). "There was also a weak positive correlation between the stage of endometriosis and the percentage of CD19+CTLA-4+ B lymphocytes." (PMID 33668701, 2021). "In addition, we explored the immune checkpoints (PDCD1, PDCD1LG2, CTLA4, TNFRSF9, and TNFRSF4) expression levels between the endometrium and endometriosis." (PMID 40165344, 2025). "Furthermore, significantly higher percentages of CD4+ CTLA4 and CD8+ CTLA4 T cells were detected in endometriosis patients with intraoperative adhesions." (PMID 38813329, 2024). "Furthermore, significantly higher percentages of CD4+/CTLA-4 and CD8+/CTLA-4 T lymphocytes were observed in patients with endometriosis and intraoperative adhesions." (PMID 35805112, 2022). "The percentages of CD4+CTLA-4+ and CD8+CTLA-4+ T lymphocytes were significantly higher in women with endometriosis and coexisting adhesion disease than in women with endometriosis but no adhesion disease." (PMID 33668701, 2021). "A positive correlation between the severity of endometriosis and the percentage of CD4+CTLA-4+ T cells (Spearman’s R = 0.531, p < 0.001), and a positive correlation between the severity of endometriosis and the percentage of CD8+CTLA-4+ T cells (Spearman’s R = 0.450, p = 0.001) were observed." (PMID 33668701, 2021). "Moreover, in patients with endometriosis and intraoperative adhesions, significantly higher percentages of CD4+CTLA-4 and CD8+CTLA-4 T cells were observed." (PMID 33668701, 2021). "In the group of patients with endometriosis associated with infertility, a negative correlation was found between the number of CD4+CTLA-4 lymphocytes and the percentage of NK cells and the percentage of NKT-like CD3+CD16+CD56+ cells." (PMID 33668701, 2021). "In CD4+ T and CD19+CTLA-4+ B cells, no such differences were observed between the group of patients with endometriosis and the control group." (PMID 33668701, 2021). "In patients with endometriosis and pelvic pain syndrome, a weak negative correlation was observed between the concentration of soluble CTLA-4 antigen in peripheral blood plasma and the percentage of CD4+CD25+highFoxp3 Treg cells (R = 0.31, p = 0.043)." (PMID 33668701, 2021). "So far, there have been no other studies published discussing CTLA-4 expression in endometriosis." (PMID 35805112, 2022). "Statistically significant changes in the percentage of T lymphocytes expressing CTLA-4 antigen in the peripheral blood of women with endometriosis indicate a significant role of negative costimulation in the development of the disease and the persistence of chronic inflammation." (PMID 33668701, 2021). "Percentages of T CD4+CTLA-4+ and B CD19+CTLA-4+ lymphocytes were not significantly different between patients with endometriosis and the control group." (PMID 33668701, 2021). "In patients with endometriosis and coexisting adhesive disease, negative correlation of T lymphocytes CD4+CTLA-4+ with the percentage of NK cells CD3-CD16+CD56+ was demonstrated (R = −0.622, p < 0.001)." (PMID 33668701, 2021).
endometriosis (continued). "Additionally, the negative correlation of CTLA-4+ T cells with the percentage of NK and NKT-like cells in women with endometriosis and infertility may indicate a different etiopathogenesis of endometriosis accompanying infertility." (PMID 33668701, 2021). "Additionally, the negative correlation of CTLA-4+ T lymphocytes and the percentage of NK and NKT-like cells in women with endometriosis and infertility may indicate a different etiopathogenesis of endometriosis accompanying infertility." (PMID 33668701, 2021).